CD69 (CD69 molecule)
Diseases named in the same sentence as CD69 in open-access papers (continued):
Sharing a sentence is not in itself a finding about the gene and the disease.
tumor (continued). "CD69 expression is associated with hypoxia in the tumor microenvironment." (PMID 32963529, 2020). "CD69 expression on tumor-associated NK cells was similar in WT and BATF3-deficient mice." (PMID 31188899, 2019). "We recently observed that tumor-associated macrophages (TAM) could effectively activate T cells to express CD69 and produce a certain amount of IFN-γ." (PMID 26895379, 2016). "Since high Hsp70 serum levels are associated with a larger GTV we speculate that CD94+/CD69+ activated NK might be able to control growth of membrane Hsp70-positive tumor cells." (PMID 26579130, 2015). "While CD69 has been implicated in promoting anti-tumor immune responses in several solid tumors by regulating NK cell activity, it may also contribute to immune evasion by enhancing the suppressive function of regulatory T cells (Tregs), thereby limiting the activity of effector T cells." (PMID 41164126, 2025). "Interestingly, mice carrying lymphoma and deficient for a gene (Hif1a) coding for a transcription factor useful for hypoxia adaptation also show reduced tumor growth in association with an increase in activated tumor-infiltrating NK cells (high expression of Ifng, Cd69, Prf1, Gzma and Gzmb)." (PMID 34680190, 2021). "Thus, we could demonstrate reduced levels of recently activated CD69+ T cells and CD25intCD4+ T cells from tumor-associated colonic mucosa compared to unaffected mucosa." (PMID 22319577, 2012). "The expression of T cell activation markers (CD25 and CD69), as well as anti-tumor cytokines (GZMB, IFNγ, and PRF1), was significantly suppressed when incubated with the supernatants of NAC-pre-treated neutrophils." (PMID 41516400, 2026). "AT3-OVA-ER cells showed less T cell–mediated killing than did AT3-OVA control cells in the different tumor/effector (T/E) ratios, along with a reduction of T cell activation (CD69) and cytotoxic markers (IFN-γ and granzyme B [GZMB])." (PMID 41289011, 2026). "High-dimensional flow cytometry of tumor-infiltrating T cells (TILs) revealed four clusters enriched for tumor-specific OT-I T cells expressing CD69 and PD-1, and differing in markers such as CD39, CD103, TCF1, TOX and TIM3." (PMID 41461987, 2026). "CD69, a marker of recently activated or tissue‐resident T cells, was decreased in several T cell types in the tumour and adjacent bowel layers." (PMID 39934971, 2025). "The activation of CAR T-cells in the presence of tumor cells was evaluated by measuring CD69 expression, an early T-cell activation marker." (PMID 40298832, 2025). "In patient tumor, CD69-expressing cells exhibited a rather low glucose dependency, a parameter associated with longer PFS, hence better prognosis, and a high FAO/AAO capacity, whereas it was the opposite for PD1-expressing cells." (PMID 41562072, 2025). "In a skin melanoma mouse model, tumor-specific epidermal CD69+ CD103+ tissue-resident memory T cells (TRMs) dynamically interacted with tumor cells, highlighting their role in immune surveillance." (PMID 40995371, 2025). "Although commonly used TRM surface markers such as CD103 and CD69 have been applied in studies of other tumour types, previous research has shown that the expression of TRM‐associated markers varies across tissues and exhibits a degree of tissue specificity." (PMID 40985995, 2025). "In this study, CD69 was significantly elevated in unvaccinated, tumor-burdened mice compared to those treated with the vaccine (p = 0.0202)." (PMID 41322193, 2025). "Tumor cell killing was accompanied by elevated expression of activation markers (i.e., CD69) and robust production of effector cytokines (i.e., IFN-γ) and cytotoxic molecules (i.e., Perforin and Granzyme B)." (PMID 40885188, 2025). "Tumor CD8+ T cells were also most enriched with CD103+CD69+ resident memory T cells (Trm; 24.6% in tumor vs. 8.4% in MPE vs. 0.3% in blood) and exhibited the highest expression of the co-inhibitory receptors PD-1, LAG-3, TIGIT, and TIM-3." (PMID 41415427, 2025).
tumor (continued). "Our data demonstrate that T cells from CAR-M-cured mice mounted robust tumor-specific responses upon re-exposure to tumor cells, characterized by rapid activation (CD69), proliferation, and effector cytokine (IL-2, IFN-γ) production." (PMID 41388305, 2025). "Our findings illustrate that lrNK cells, characterized by CXCR6 and CD69 expression, are more abundant in non-tumor areas during eHCC but decline with disease progression, consistent with previous reports." (PMID 40547009, 2025). "Of note, the only difference we observed was in the tumor of one patient (patient GS.1225), where CD69 expression on CD4 and CD8 T cells was higher in the resected tissue compared to the UA tissue." (PMID 40002198, 2025). "Advanced HCC stages demonstrated altered NK cell phenotypes, with reduced cytotoxic activation (CD16) and increased residency markers (CXCR6/CD69) in tumor-isolated lymphocytes." (PMID 40547009, 2025). "Mechanistic dissection of these pathways has prompted efforts to develop a standardized “TRM immunoscore” that integrates phenotypic composition (CD103, CD69, CD49a) with spatial localization relative to tumor epithelium and vasculature." (PMID 41479900, 2025). "In a 4T1 breast cancer model, using antibodies to neutralize intratumoral CXCL16 not only liberated CXCR6+ effector-memory cells from the primary tumor but also led to their accumulation as CD103+CD69+ TRM cells in the lungs." (PMID 40862776, 2025). "Further, GSE34573 dataset, including four normal samples and 16 tumor samples, showed that both CD69 and SELL were over-expression in NPC." (PMID 40158161, 2025). "We found that CD69− T cells within tumors are linked to better patient outcomes, likely due to reduced exhaustion, while CD69+CD103+CD8+ T cells in non-tumor liver tissues play a key role in immune surveillance." (PMID 40361474, 2025). "Accordingly, a reduced PD-1 expression on CD69− populations correlated with an increased frequency of these cells, reinforcing the concept that CD69− T cells serve as a relatively “functional” subset capable of effectively contributing to anti-tumor response." (PMID 40361474, 2025). "Co-culturing of CD19CAR Jurkat cells and CD19-expressing Nalm-6 tumor cells showed that a curcumin concentration of 1 μM significantly increased CD69 expression compared to the control group (0 μM curcumin)." (PMID 40298832, 2025). "The FLIM data correlated well with the standard assays of immunotherapy drug response in vitro, including morphological changes, the T-cells activation marker CD69, and the tumor cell proliferation index Ki67." (PMID 39851525, 2025). "Our findings help resolve this complexity by revealing that CD69− T cells within the tumor—a subset typically considered to be circulating or residing less in tissues—were strongly associated with improved RFS." (PMID 40361474, 2025). "T cells isolated from tumor tissues have been shown to express more CD69 than circulating or non-tumor tissue T cells." (PMID 41322193, 2025). "FVS staining of the cells after organoid digestion indicated that the organoid group, with a significantly increased proportion of cytotoxic CD69+ T cells, showed increased numbers of dead tumor cells, demonstrating anti-PD-1-dependent tumor killing activity." (PMID 41551162, 2025). "Peripheral NK cells from obese patients displayed elevated activation markers such as CD69 and granzyme B but defective degranulation and reduced tumor-killing capacity." (PMID 41516046, 2025). "In the subset of patients with an increase in the percentage of CD38+ lymphocytes in response to modakafusp alfa, there were also increases in CD8+ and CD4+ T-cell activation (%CD69) as well as CD8+ T-cell cytotoxic function (%GzB) in the tumor biopsies." (PMID 41445795, 2025). "The immune cells from tumor lesions were also isolated, and we observed enhanced CD69 expression in T cells from ANX005‐treated mice, indicating improved T cell activation." (PMID 40171991, 2025).
tumor (continued). "In this context, CD69+ NK cells potentially represent a fraction of tissue-resident NK cells, especially within the TME and in tumor-associated compartments, like ascites." (PMID 41221283, 2025). "By bridging IL-13Rα2+ tumor cells and CD3ε on T cells, the BiTE induces T-cell activation (CD69/CD25 upregulation), GZMB release, and production of inflammatory cytokines (IFN-γ, TNF-α), culminating in tumor-specific lysis." (PMID 41209565, 2025). "ActRIIA high CD8+ T cells expressed CD69 CD11c CD49b, indicative of their tissue resident feature in the tumor." (PMID 39727149, 2025). "Activation of lymphocytes, with the focus on subsets (CD8 T cells, NK cells and NKT cells) that are crucial in anti-tumor immune responses, was scored based on early-to-intermediate activation markers CD69, CD25, CD38." (PMID 40691137, 2025). "The beneficial impact of CD69− T cells within the tumor and CD69+CD103+CD8+ T cells in liver tissues underscores the complexity of T cell-mediated immunity in HCC and the importance of spatial context." (PMID 40361474, 2025). "The expression levels of PD-L1 and PD-1 were significantly elevated in tumor tissues, whereas CD69, IFN-γ, and TNF-α levels were markedly reduced (all p < 0.05)." (PMID 41445633, 2025). "Combining Tubastatin A (an HDAC6/8‐selective inhibitor) with acetate increases H3K27ac signal, markedly up‐regulates core TRM markers including CD103 and CD69, and enhances the tissue‐residency capacity of virus‐ or tumor‐specific CD8+ T cells." (PMID 41361844, 2025). "MP4 or PD1 single treatment inhibited tumor growth in a similar pattern, with enhanced infiltration and activation (CD69+) of CD8 T cells into the TME." (PMID 40034859, 2025). "CD47 acts as a “don't eat me” signal, and its blockade enhances macrophage activation (CD69+) and phagocytosis against tumor cells." (PMID 40487639, 2025). "When focusing on liver resident NK (lrNK) cells, characterized by the co-expression of CXCR6/CD69, we found that non-tumor areas in eHCC contained a higher percentage of lrNK cells, both CD56dim and CD56bright, than in tumor areas." (PMID 40547009, 2025). "Both CD4+ T‐helper and CD8+ T‐cytotoxic cells from mice with large tumours expressed slightly elevated activation (CD69) and proliferative (IFN‐γ, Ki67) markers compared to mice with small tumours, indicating metabolic changes." (PMID 40112892, 2025). "Conversely, SURF4 overexpression in T cells significantly reduced the expression of activation markers (CD3D, CD69) and anti-tumor proteins (GZMB), while simultaneously suppressing the p-STING/p-IRF3 axis." (PMID 40846839, 2025). "22.0405.aF treatment induced statistically significant activation of tumor-resident NK cells, measured as an increased percentage of NK cells expressing CD69 or IFN-γ compared to vehicle-treated tumors." (PMID 41479906, 2025). "A substantial proportion of the tumor‐infiltrating memory T cells differentiated from central memory T cells (CD44+CD62L+CD69−) to effector memory T cells (CD44+CD62L−CD69−)." (PMID 39761175, 2025). "Our study also found that treatment with CV1 in combination with CDH17-CAR-NK92 led to an increase in CD69+ and CD86+ macrophages, potently implicating the enhanced antitumor activity of tumor-associated macrophages." (PMID 40487639, 2025). "Tumor NKdim cells of the aHCCbp group had higher expression of the activation marker NKG2D and of the markers CXCR6/CD69 than aHCC, associated with liver residency but in contrast had reduced expression of the activation marker CD16." (PMID 40547009, 2025). "Flow cytometry was used to determine the proportions of CD3+ T cells, CD8+ T cells, and CD8+CD69+ T cells in tumor tissues." (PMID 40819134, 2025). "Coculture of CD8+ OT-I T cells with either Usp22 KO MC38 or RM1 cancer cells with stable OVA expression enhanced CD8+ T cell activation, indicated by elevated CD69 expression and tumor cell killing." (PMID 41252204, 2025).
tumor (continued). "T cell accumulation was significantly higher in the spleen and within the tumor microenvironment, with elevation in activation markers such as Interleukin-17, CD69, NKG2D, and FasL and a decrease in Interleukin-10 and FoxP3 expression." (PMID 41096863, 2025). "In line with increased tissue retention, percentages of the residency markers CD69 and CD49a were distinctly higher in tumor infiltrating CAR NK cells and control NK cells." (PMID 38745250, 2024). "The activation, degranulation and proliferation of armored-T cells after combination with antibody drugs and tumor cells were investigated by determining the expression of CD69 and CD107a." (PMID 38953027, 2024). "There was a statistically significant change in copper/zinc ratio and CD19+CD69+ tumor T lymphocytes." (PMID 38256645, 2024). "The combination therapy downregulated immune response suppressors such as ApoE, CD69 and Cxcr4, which altered the transcriptome of CD11b+ cells to restore their anti-tumor function." (PMID 39239650, 2024). "The rise in CD69+ B cells in both spleen and tumor tissue indicates an ongoing B cell activation and clonal expansion in the context of generating an adaptive immune response." (PMID 39791721, 2024). "We then monitored the expression of activation markers CD69 and Ki67 during tumor growth in the spleen." (PMID 39196934, 2024). "When expressed in Jurkat cells, the A4 and C1 TCRs responded to MR1*01-expressing tumor cell lines, as shown by upregulation of CD69." (PMID 39445059, 2024). "The serum zinc level significantly positively correlated with the percentage of CD19+CD69+ in tumor samples and CD4+CD25+ in node samples." (PMID 38256645, 2024). "The rising number of FO B cells in the tumor group compared to the control in spleen tissue was accompanied by an increasing number of activated CD69+ B cells, GC B cells, and plasma cells." (PMID 39791721, 2024). "To do so, we evaluated the expression of activation markers CD39+ and CD69+ on the CAR‐T cell product as well as on CAR T cells isolated from tumour and spleen of treated mice at day 40, post treatment." (PMID 39548594, 2024). "Although the time frame afforded by photo-labeling is too short to fully assess tissue-residency, CD49a+ intratumoral NK cells also upregulated CD69, consistent with becoming resident within the tumor." (PMID 38267402, 2024). "Meanwhile, the flow cytometry results showed that compared to the S100A10-sh-NC group, the proliferation capacity (Ki67) and cell viability (CD69) of CD8+ T cells in tumor tissue were enhanced in the S100A10-sh group." (PMID 39117605, 2024). "Following the interaction of CAR-NK cells with tumor cells, the up-regulation of CD69 expression typically accompanies cell activation." (PMID 38475814, 2024). "The expression of CD69 in CAR-NK cells increased compared to NK cells under specific tumor load conditions, with the highest activation level observed in CD19/CD20 dual-targeted CAR-NK cells." (PMID 38475814, 2024). "Tissue-resident-memory (TRM) T cells (CD69+CD103+) within tumours are another T cell subset of interest for immunotherapy research." (PMID 38986249, 2024). "Consistently, a higher proportion of tumor‐infiltrating T cells exhibited expression of the T cell activation marker CD69 and effector molecules GZMB and IFNγ in the combination treatment group as compared with to the control or single drug treatment group." (PMID 39412086, 2024). "When T cells are activated by corresponding tumour antigens, they express surface activation markers such as 41BB, CD69 and CD25 and produce effector molecules such as IL-2, TNF-α, IFN-γ, perforin and granzymes." (PMID 38727812, 2024). "Further, within both CD8+ and CD4+ T cells – both within the tumor and spleen – we observed a shift towards Ki67+CD69+ and Ki67+PD-1+ cells, indicating the prevalence of both proliferating and activated lymphocytes in response to AP-diABZI." (PMID 38766114, 2024).
tumor (continued). "The increase in CD69+ B cells corresponded with a tremendous rise in the absolute proportion of B220+CD95+GL7+ GC B cells among all B220+ cells in tumor-bearing mice in lymph nodes and spleen throughout the observation period." (PMID 39791721, 2024). "Human NK cells co-cultured with VSV-NDV-infected tumor cells demonstrated an increase in CD69 and IFN-γ expression." (PMID 39410025, 2024). "Cells within the TEff_6 subset, exhibiting high programmed cell death protein 1 (PD-1) and CD69 expression, potentially reflecting an exhausted or terminally differentiated phenotype, were present at similar frequencies between the tumor types." (PMID 38053333, 2024). "Immune changes in the TME associated with improved treatment outcomes were subtle but included increases in proinflammatory innate immune cells and activated CD8+CD69+ T cells and varied between the two tumor models." (PMID 38312842, 2024). "The flow-cytometry results showed that expression levels of CD137 and CD69 significantly increased in TCR-T cells cocultured with corresponding autologous tumour cells." (PMID 38727812, 2024). "The results from flow cytometry revealed that compared to the S100A10-sh-NC group, in the S100A10-sh group, the proliferative capacity (Ki67) and cell vitality (CD69) of CD8+ T cells in the tumor tissue increased." (PMID 39117605, 2024). "CD69 + T cells display another type of activated cells for which an important role in anti-tumor immunity has been reported." (PMID 38987735, 2024). "CD69 can be understood as an immunomodulator following B cell activation by tumor antigens, serving as an early B cell activation marker, a prerequisite for subsequent adaptive humoral immune responses." (PMID 39791721, 2024). "Despite this, the percentage of CD69-expressing CD8+ lymphocytes in the spleens of the affective treatment group with tumours smaller than 300 mg was statistically higher than the mild and no-effect groups (>300 mg tumour size) and isotype control." (PMID 37887559, 2023). "Together, these data support the expression of CD69 on CD3+ T cells in the tumor and spleen tissues of GBM-bearing mice following ICI treatment and further support its use as a putative biomarker of immunotherapy response." (PMID 37426447, 2023). "We moreover observed a similar increase in early activated CD69+ NK cells in the combination treatment groups, suggesting greater tumour infiltration by activated NK cells." (PMID 37153626, 2023). "In this case, the CAR construct can be co-expressed (e.g.: CD69) or disrupt the targeted gene (e.g.: PD-1), thereby theoretically improving anti-tumor potency depending on what is more desirable." (PMID 37277433, 2023). "CD69+CD8+ TM cells had higher levels of Ki67, CD223 (LAG3), and CD279 (PD-1) than did CD69−CD8+ TM cells, suggesting these CD69+CD8+ TM cells were highly proliferating tumor-reactive T cells." (PMID 36759517, 2023). "We also observed higher frequency of activated CD69+ CD44+ CD8+ splenic T cells in tumor-bearing mice treated with the combination of 5AZADC and ADU-S100 compared to those treated with either single agent." (PMID 36949064, 2023). "Immune cell profiling through flow cytometry showed that relative to the vehicle, verteporfin induced a higher ratio of tumor-associated macrophage (TAM) M1/M2 and increased the percentage of activated CD8 T cell population (CD8+CD25+ and CD8+CD69+)." (PMID 37173920, 2023). "Flow cytometry analysis revealed a significant surge in cells expressing activation markers CD69, CD107a, and FasL upon encountering tumor cells, indicating robust T-cell activation and cytotoxicity." (PMID 37894816, 2023). "The increase of CD69+ CD8 T cells in tumor-draining lymph node in the combination group also confirmed that AlloDCs can initiate the T cells response." (PMID 37654492, 2023). "The expression of the activation marker CD69 on tumor-infiltrating T cells and NK cells significantly increased following immunization with ProLNG-001." (PMID 37766179, 2023).